AFG3L2 (AFG3 like matrix AAA peptidase subunit 2)
Description:
Catalytic component of the m-AAA protease, a protease that plays a key role in proteostasis of inner mitochondrial membrane proteins, and which is essential for axonal and neuron development. AFG3L2 possesses both ATPase and protease activities: the ATPase activity is required to unfold substrates, threading them into the internal proteolytic cavity for hydrolysis into small peptide fragments. The m-AAA protease carries out quality control in the inner membrane of the mitochondria by mediating degradation of mistranslated or misfolded polypeptides. The m-AAA protease complex also promotes the processing and maturation of mitochondrial proteins, such as MRPL32/bL32m, PINK1 and SP7. Mediates protein maturation of the mitochondrial ribosomal subunit MRPL32/bL32m by catalyzing the cleavage of the presequence of MRPL32/bL32m prior to assembly into the mitochondrial ribosome. Required for SPG7 maturation into its active mature form after SPG7 cleavage by mitochondrial-processing peptidase (MPP). Required for the maturation of PINK1 into its 52kDa mature form after its cleavage by mitochondrial-processing peptidase (MPP). Acts as a regulator of calcium in neurons by mediating degradation of SMDT1/EMRE before its assembly with the uniporter complex, limiting the availability of SMDT1/EMRE for MCU assembly and promoting efficient assembly of gatekeeper subunits with MCU. Promotes the proteolytic degradation of GHITM upon hyperpolarization of mitochondria: progressive GHITM degradation leads to respiratory complex I degradation and broad reshaping of the mitochondrial proteome by AFG3L2. Also acts as a regulator of mitochondrial glutathione homeostasis by mediating cleavage and degradation of SLC25A39. SLC25A39 cleavage is prevented when SLC25A39 binds iron-sulfur. Also acts as a regulator of carnitine biosynthesis by mediating cleavage and degradation of SLC25A45. Involved in the regulation of OMA1-dependent processing of OPA1. May act by mediating processing of OMA1 precursor, participating in OMA1 maturation.
Synonyms: SPAX5; OPA12; SCA28
Tractability: Small molecule: a structure with a bound ligand is known. Antibody: UniProt predicts a signal peptide or a membrane-spanning region. PROTAC: ubiquitination databases record sites on it; its protein half-life has been measured.
Target class: Enzyme; Hydrolase
Gene: Protein-coding gene on chromosome 18 (12,328,932 to 12,377,473, reverse strand). Ensembl gene ENSG00000141385.
Subcellular location: Mitochondrion inner membrane
Subcellular location (Human Protein Atlas): Mitochondria; Calyx; Connecting piece; Mid piece; Perinuclear theca; Principal piece
Pathways (Reactome):
Metabolism of proteins: Mitochondrial protein degradation
Transport of small molecules: Processing of SMDT1
Gene Ontology:
Molecular function: ATP hydrolysis activity; metalloendopeptidase activity; metallopeptidase activity; protein binding; ATP binding; ATP-dependent peptidase activity; zinc ion binding
Biological process: axonogenesis; calcium import into the mitochondrion; cellular response to glutathione; membrane protein proteolysis; mitochondrial calcium ion homeostasis; mitochondrial protein processing; mitochondrial protein quality control; protein catabolic process; protein maturation; proteolysis; regulation of calcium import into the mitochondrion; protein autoprocessing; protein processing
Cellular component: m-AAA complex; mitochondrial inner membrane; mitochondrion; membrane
Genetic constraint (gnomAD): Loss-of-function variants: 50 observed, 87.45 expected, observed/expected ratio (o/e) 0.57, 90% interval 0.46 to 0.72. The upper end of that interval is the gene's LOEUF score, 0.72, which puts it in group 2 of 6, group 1 being the genes least tolerant of losing a copy. Missense variants: 715 observed, 978.3 expected, observed/expected ratio (o/e) 0.73, 90% interval 0.69 to 0.78. Synonymous variants: 365 observed, 360.84 expected, observed/expected ratio (o/e) 1.01, 90% interval 0.93 to 1.1.
Gene-disease validity (ClinGen):
ClinGen rates the evidence that AFG3L2 causes each of these diseases.
AFG3L2-related optic atrophy and/or spastic ataxia spectrum (semidominant): Definitive. Any disorder caused by a heterozygous variant or biallelic variants in the AFG3L2 gene and characterized by a spectrum of phenotypes including optic atrophy and/or spastic ataxia.
Homologues: Orthologues: chimpanzee AFG3L2 (99% identical), macaque AFG3L2 (99% identical), dog AFG3L2 (95% identical), pig AFG3L2 (95% identical), rat Afg3l2 (93% identical), mouse Afg3l2 (93% identical), guinea pig AFG3L2 (90% identical), rabbit AFG3L2 (83% identical), tropical clawed frog afg3l2 (82% identical), zebrafish afg3l2 (81% identical). Paralogues in human: SPG7 (40% identical), YME1L1 (30% identical).
Diseases named in the same sentence as AFG3L2 in open-access papers:
AFG3L2 is named in the same sentence as 78 diseases in open-access papers, as found by Europe PMC text mining. Sharing a sentence is not in itself a finding about the gene and the disease. The quoted sentences say what the papers report.
spinocerebellar ataxia (32 papers, 2010 to 2026). "We face early diagnostic challenges of ataxia and optic neuropathy due to asymptomatic parents and variable clinical manifestations due to heterozygosity/homozygosity of AFG3L2 mutations." (PMID 38012514, 2024). "Unique frameshift AFG3L2 mutation, c.1958dupT in exon 15, causes mild Parkinsonism with cognitive decline, cerebellar ataxia, bradykinesia, and polyneuropathy." (PMID 38012514, 2024). "It upregulates glutamate receptor EAAT2 in the astrocytic glial cells and ameliorates ataxia in heterozygous mutated AFG3L2 by inhibiting glutamate excitotoxicity and creating healthy Purkinje cell and glial connections." (PMID 38012514, 2024). "The heterozygous missense mutations in the AFG3L2 gene cause spinocerebellar ataxia (SCA28) disease characterized by cerebellar dysfunction due to Purkinje cell degeneration." (PMID 36389399, 2022). "Mutations in the genes coding for AFG3L2 and its binding partner paraplegin are associated with a form of spinocerebellar ataxia (SCA28) and a form of hereditary spastic paraplegia (SPG7), respectively." (PMID 32492073, 2020). "Variants in AFG3L2 produce dominant spinocerebellar ataxia and recessively inherited spastic-neuropathy syndrome (SCA28), while SPG7 induces recessive inherited spastic paraplegia." (PMID 33426505, 2020). "A reduction of calcium influx into the cytosol of Purkinje cells rescues ataxia in an AFG3L2-deficient mouse model." (PMID 29451229, 2018). "Meanwhile, 13 missense mutations of the ATPase family gene 3-like 2 gene (AFG3L2) have been reported to cause ataxia." (PMID 26677414, 2015). "No role for this gene has been reported so far in mutant huntingtin aggregation, but mutations in AFG3L2 cause the dominant spinocerebellar ataxia, SCA28, a neurodegenerative disorder characterized by Purkinje cell degeneration." (PMID 21915392, 2011). "Heterozygous mutations in AFG3L2 were previously found to cause a disorder involving the Purkinje cells of the cerebellum resulting in ataxia." (PMID 22022284, 2011). "Similarly, in a Taiwanese cohort, only one patient was reported for AFG3L2 mutation among 133 cerebellar ataxia patients." (PMID 38012514, 2024). "However, mutations in AFG3L2 have been shown to cause spinocerebellar ataxia through the development of mitochondrial proteotoxicity." (PMID 32632177, 2020). "Mutations in the genes encoding Afg3l2 and Paraplegin cause spinocerebellar ataxia (SCA28) and hereditary spastic paraplegia (HSP) respectively, but the interplay between these proteins, their substrates, and the pathways influenced by mutations in their respective genes are poorly understood." (PMID 33075064, 2020). "Moreover, a severe phenotype combining features of spastic paraplegia and ataxia associated with myoclonic epilepsy (SPAX5) has been linked to a homozygous mutation in AFG3L2." (PMID 27911893, 2016). "However, neither Paraplegin nor AFG3L2 is completely dispensable as mutations in the gene encoding Paraplegin cause a recessive form of hereditary spastic paraplegia, whereas heterozygous mutations in the gene encoding AFG3L2 cause a dominant form of spinocerebellar ataxia." (PMID 24288463, 2013). "AFG3L2 is a good example when a mitochondrial protease result in both dominant and recessive neurodegenerative diseases leading to ataxia and spastic paraparesis (SCA28 and SPAX5)." (PMID 40051915, 2025). "Previous reports have found that the conditional deletion of AFG3L2 which encodes one of the subunits of the m-AAA protease in Bergmann glia cell leads to PCs degeneration and ataxia." (PMID 37688710, 2024). "SCA28 is a rare type of ataxia, and AFG3L2 has been shown to be involved with this disorder in several studies across the world." (PMID 38012514, 2024). "In our current work, we inactivated the Drosophila AFG3L2 gene to create models of two of these syndromes: spastic ataxia neuropathy syndrome and spinocerebellar ataxia." (PMID 33075064, 2020).
spinocerebellar ataxia (continued). "Pathogenic mutations that disrupt the AFG3L2 quality control complex are associated with human diseases: hereditary spastic paraplegia (HSP), spastic ataxia (SPAX5), spinocerebellar ataxia (SCA28), and progressive external ophthalmoplegia (PEO)." (PMID 30683687, 2019). "Remarkably, the ataxia in Afg3l2 heterozygous mice is ameliorated by administration of the antibiotic ceftriaxone, which promotes synaptic glutamate clearance by increasing the expression of the glutamate receptor EAAT2 in astrocytes." (PMID 30989755, 2019). "Two patients with indolent ataxia and CPEO with two different heterozygous mutations in AFG3L2 were recently identified." (PMID 28324239, 2017). "AFG3L2 encodes another subunit of m-AAA protease which interacts with paraplegin, and was originally associated with spinocerebellar ataxia." (PMID 28324239, 2017). "AFG3L2 mutations, although are related to cerebellar ataxias, does not exhibit polyglutamine repeats like the majority of SCA genes." (PMID 38012514, 2024). "It is reported that the absence of AFG3L2 increases the cytosolic calcium influx in the Purkinje cells causing ataxia due to constitutively active MCU-EMRE assembly." (PMID 38012514, 2024). "Reducing cellular calcium influx is able to improve ataxia in the Afg3l2 haploinsufficient mice." (PMID 37374132, 2023). "AFG3L2 is mutated in a dominant form of SCA28, and in early‐onset recessive syndromes characterized by severe spastic‐ataxia, epilepsy, and premature death." (PMID 30989755, 2019). "Mutations in AFG3L2 are responsible for the SCA28 and SPAX5 forms of spinocerebellar ataxia." (PMID 26539208, 2015). "Mutations in AFG3L2 cause autosomal dominant spinocerebellar ataxia 28 (SCA28; MIM #610246), a recently recognized and rare disorder characterized clinically by adult-onset dysarthria, ptosis and cerebellar ataxia." (PMID 22022284, 2011). "For AFG3L2, these include autosomal dominant hereditary spinocerebellar ataxia type 28 (SCA28, MIM #610246), autosomal recessive spastic ataxia 5 (SPAX5, MIM #614487) and optic atrophy 12 (OPA12, MIM #618977)." (PMID 40857737, 2025). "It is worth noting that mitochondrial dysfunction has also been identified in other forms of Spinocerebellar Ataxia and spastic ataxias, including Friedreich’s ataxia (FXN), SCA type 28 (AFG3L2), and Autosomal Recessive Spastic Ataxia type 4 (MTPAP)." (PMID 40757543, 2024). "For example, accumulation of EMRE protein in the absence of mitochondrial AAA-proteases AFG3L2 and SPG7, whose mutations are associated with spinocerebellar ataxia and hereditary spastic paraplegia, is responsible for mitochondrial Ca2+ overload and may contribute to neuronal loss." (PMID 32769116, 2020).
spinocerebellar ataxia type 28 (21 papers, 2011 to 2025). Spinocerebellar ataxia type 28 (SCA28) is a very rare subtype of type I autosomal dominant cerebellar ataxia (ADCA type I). "Mutations in AFG3L2 are implicated in a spectrum of diseases, including spinocerebellar ataxia type 28 (SCA28) and spastic ataxia 5 (SPAX5), as well as other systemic conditions." (PMID 40051915, 2025). "One case with hereditary spastic paraplegia (SPG5) gene mutation and one case with spinocerebellar ataxia type 28 (AFG3L2) gene mutation (p.R632X)." (PMID 29348930, 2017). "Mutations in AFG3L2 may lead to a clinical spectrum: dominant variants are associated with late onset spinocerebellar ataxia type 28 (SCA28; MIM: 610246), whereas pathogenic biallelic variants lead to spastic ataxia 5 (SPAX5; MIM: #614487)." (PMID 40051915, 2025). "For example, mutations in AFG3L2 lead to spinocerebellar ataxia type 28, or spastic ataxia 5; mutations in paraplegin are the causative agents of hereditary spastic paraplegia and progressive external ophthalmoplegia; and mutations in both AFG3L2 and SPG7 occur in dominant optic atrophy (DOA)." (PMID 34360841, 2021). "Recessive mutations in SPG7, encoding paraplegin, lead to hereditary spastic paraplegia (HSP), a neurodegenerative disease affecting the long corticospinal motor axons, while dominant mutations in AFG3L2 cause spinocerebellar ataxia type 28 (SCA28), associated with atrophy of the cerebellum." (PMID 27911893, 2016). "As a component of the m-AAA protease complex, paraplegin associates with AFG3L2 subunits encoded by the AFG3L2 gene—mutations in which are responsible for autosomal dominant spinocerebellar ataxia type 28 (SCA28)." (PMID 41149856, 2025). "Mutations in AFG3L2 cause spinocerebellar ataxia type 28 (SCA28), a juvenile-onset disease featuring progressive gait and limb ataxia with abnormal eye movement." (PMID 35463435, 2022). "Of note, missense mutations in AFG3L2/OPA12 are also known to cause the unrelated disorders spinocerebellar ataxia type 28 (SCA28) and spastic ataxia syndrome 5 (SPAX5) but these mutations are generally localized within the proteolytic domain of the protein." (PMID 34867178, 2021). "Previous work has shown that heterozygous mutations in the human AFG3L2 gene cause spinocerebellar ataxia type 28 (SCA28), and haploinsufficiency of AFG3L2 in mice has been shown to cause mitochondria-mediated Purkinje cell dark degeneration." (PMID 33075064, 2020). "Heterozygous mutations in AFG3L2 cause spinocerebellar ataxia type 28 (SCA28) and mitochondrial respiratory chain deficiency." (PMID 32858900, 2020). "Mutations in AFG3L2 coding for the second m-AAA protease subunit are associated with spinocerebellar ataxia type 28 (SCA28), which is accompanied by the loss of Purkinje cells." (PMID 29451229, 2018). "For example, at least 17 single amino acid substitutions in AFG3L2 have been linked to the development of spinocerebellar ataxia type 28 (SCA28), a disorder characterized by imbalance, slurred speech and lack of limb coordination." (PMID 28589125, 2017). "Spinocerebellar ataxia type 28 (SCA28) is related to mutations of the ATPase family gene 3-like 2 gene (AFG3L2)." (PMID 26677414, 2015). "Heterozygous loss-of-function mutations in AFG3L2 cause autosomal-dominant spinocerebellar ataxia type 28 (SCA28), a disorder whose phenotype is strikingly different from that of our patients." (PMID 22022284, 2011). "This review delineates the cellular functions of AFG3L2 and its dysfunction that leads to major clinical outcomes, which include spinocerebellar ataxia type 28, spastic ataxia type 5, and optic atrophy type 12." (PMID 38012514, 2024). "Extensive investigations have shown that heterozygous mutations in AFG3L2 are responsible for autosomal dominant spinocerebellar ataxia type 28 (SCA28), while homozygous mutations in AFG3L2 are associated with autosomal recessive spastic ataxia syndrome (SPAX5)." (PMID 35970831, 2022).
spinocerebellar ataxia type 28 (continued). "Interestingly, the identified mutation localizes close to the AAA domain of AFG3L2, while those localized in the proteolytic domain cause dominant spinocerebellar ataxia type 28 (SCA28) or recessive spastic ataxia with epilepsy (SPAX5)." (PMID 32600459, 2020). "This review discusses the multifaceted roles of AFG3L2 in mitochondrial physiology and its role primarily in spinocerebellar ataxia type 28 (SCA28) and other diseases." (PMID 38012514, 2024). "Mutations in AFG3L2 and SPG7 have been initially identified as the cause of spinocerebellar ataxia type 28 (SCA28) and spastic ataxia type 5, and hereditary spastic paraplegia type- 7 (HSP7), respectively." (PMID 33806088, 2021). "Heterozygous mutations of AFG3L2 contribute to autosomal dominant hereditary spinocerebellar ataxia type 28 (SCA28, MIM #610246) and optic atrophy-12 (OPA12, MIM #604581)." (PMID 36475414, 2022).
hereditary spastic paraplegia (15 papers, 2010 to 2025). Hereditary spastic paraplegias (HSP) comprise a genetically and clinically heterogeneous group of neurodegenerative disorders characterized by progressive spasticity and hyperreflexia of the lower limbs. "AFG3L2 is a candidate gene for hereditary spastic paraplegias or neurodegenerative disorders as well as spastic ataxia–neuropathy syndrome." (PMID 39941288, 2025). "Hereditary spastic paraparesis (HSP) is mainly associated with the dysfunction of paraplegin, whereas mutation of AFG3L2 is involved with primarily causing SCA28." (PMID 38012514, 2024). "The m-AAA displays a hexameric ring structure that in humans can be a homo-oligomer formed by AFG3L2 only, or a hetero-oligomer formed by AFG3L2 and Paraplegin (a paralog of AFG3L2 encoded by the SPG7 gene, whose loss-of-function causes an autosomal recessive form of hereditary spastic paraplegia)." (PMID 23777634, 2013). "Mutations in AFG3L2 are associated with dominant spinocerebellar ataxia (SCA28) characterized by the loss of Purkinje cells, whereas mutations in SPG7 cause a recessive form of hereditary spastic paraplegia (HSP7) with motor neurons of the cortico-spinal tract being predominantly affected." (PMID 29451229, 2018).
spastic ataxia (11 papers, 2011 to 2026). "This study employs a multi-omics approach to investigate the biochemical impact of AFG3L2 mutations in immortalized lymphoblastoid cell lines derived from a patient with biallelic variants leading to spastic ataxia (SPAX5)." (PMID 40051915, 2025). "Neurodegeneration including optic nerve atrophy, spastic ataxia, and progressive cerebral atrophy is a clinical hallmark in patients suffering from pathogenic AFG3L2 variants." (PMID 40051915, 2025). "Homozygous mutations of AFG3L2 are also implicated in autosomal recessive spastic ataxia-5 (SPAX5, MIM #614487)." (PMID 36475414, 2022). "Using emerging techniques of whole-exome sequencing we discovered that homozygous mutations in the AFG3L2 gene caused spastic ataxia in two brothers of a consanguineous family." (PMID 22022284, 2011). "The mutation specifically at Y616C [c.1847A > G] of AFG3L2 leads to phenotypically different manifestations from SCA28 and causes spastic ataxia." (PMID 38012514, 2024). "Screening of the entire SPG7 and AFG3L2 genes in genetically undiagnosed cases of MND and spastic ataxia may help to increase the diagnostic yield." (PMID 41877227, 2026). "In this study, there was no causative mutation associated with spastic ataxia, such as SACS/VAMP1/KIF1C/MARS2/MTPAP/AFG3L2(AR), detected." (PMID 35572931, 2022).